OLIG2 (oligodendrocyte transcription factor 2)
Description:
Required for oligodendrocyte and motor neuron specification in the spinal cord, as well as for the development of somatic motor neurons in the hindbrain. Works in coordination with ZNF488 to promote oligodendrocyte differentiation. Orchestrates progenitor cell fates during cortical gliogenesis and gliomagenesis. In cooperation with OLIG2, activates oligodendrocyte precursor cells (OPCs) formation while repressing the generation of olfactory bulb interneuron intermediate progenitors (OBIN) generation through transcriptional regulation of GSX2. Mechanistically, binds and silences multiple conserved enhancer elements of GSX2. Cooperates with OLIG1 to establish the pMN domain of the embryonic neural tube. Antagonist of V2 interneuron and of NKX2-2-induced V3 interneuron development.
Synonyms: Oligo2; bHLHb1; bHLHe19; PRKCBP2; RACK17
Tractability: No criterion of Open Targets' tractability assessment is met for any kind of drug.
Gene: Protein-coding gene on chromosome 21 (33,025,327 to 33,029,196, forward strand). Ensembl gene ENSG00000205927.
Subcellular location: Nucleus; Cytoplasm
Subcellular location (Human Protein Atlas): Nucleoplasm; Plasma membrane
Gene Ontology:
Molecular function: protein binding; sequence-specific double-stranded DNA binding; DNA-binding transcription factor activity, RNA polymerase II-specific; E-box binding; DNA-binding transcription factor activity; HMG box domain binding; identical protein binding; protein dimerization activity
Biological process: axon development; positive regulation of transcription by RNA polymerase II; sensory organ development; myelination; neuron differentiation; oligodendrocyte cell fate specification; oligodendrocyte differentiation; regulation of DNA-templated transcription
Cellular component: chromatin; nucleus; cytoplasm
Genetic constraint (gnomAD): Loss-of-function variants: 12 observed, 9.63 expected, observed/expected ratio (o/e) 1.25, 90% interval 0.79 to 1.84. That is too few expected variants to judge how well the gene tolerates losing a copy. Missense variants: 415 observed, 387.83 expected, observed/expected ratio (o/e) 1.07, 90% interval 0.99 to 1.16. Synonymous variants: 250 observed, 190.16 expected, observed/expected ratio (o/e) 1.31, 90% interval 1.18 to 1.46.
Homologues: Orthologues: macaque OLIG2 (99% identical), pig OLIG2 (97% identical), dog OLIG2 (96% identical), mouse Olig2 (96% identical), rat Olig2 (96% identical), guinea pig OLIG2 (80% identical), zebrafish olig2 (62% identical), tropical clawed frog olig2 (60% identical), Drosophila melanogaster ato (13% identical), Caenorhabditis elegans ngn-1 (13% identical), Drosophila melanogaster tap (12% identical), Drosophila melanogaster amos (11% identical), and 1 more. Paralogues in human: OLIG3 (48% identical), BHLHE22 (29% identical), OLIG1 (25% identical), BHLHE23 (24% identical), NEUROD4 (19% identical), NEUROD2 (18% identical), NEUROD1 (17% identical), NEUROD6 (16% identical), ATOH1 (16% identical), NEUROG2 (14% identical), NEUROG1 (13% identical), ATOH8 (12% identical), and 3 more.
Diseases named in the same sentence as OLIG2 in open-access papers:
OLIG2 is named in the same sentence as 138 diseases in open-access papers, as found by Europe PMC text mining. Sharing a sentence is not in itself a finding about the gene and the disease. The quoted sentences say what the papers report.
glioma (218 papers, 2005 to 2026). A benign or malignant brain and spinal cord tumor that arises from glial cells (astrocytes, oligodendrocytes, ependymal cells). "OLIG2 upregulation is associated with more prolonged survival, potentially reflecting its role in maintaining a less aggressive, oligodendrocyte-like glioma phenotype." (PMID 40282990, 2025). "ATRX loss and OLIG2 overexpression support glioma stemness and chromatin remodeling, while MGMT activity influences chemoresistance." (PMID 40282990, 2025). "In a predisposed glioblastoma animal model, ablation of mitotic OLIG2-positive progenitor cells halted tumor growth, identifying these progenitors as seeds for glioma propagation." (PMID 40428395, 2025). "In Olig2-deficient glioma models, the downregulation of PDGFRA signaling is accompanied by feedback upregulation of the EGFR pathway to sustain tumor growth." (PMID 40428395, 2025). "OLIG2 has also been implicated in glioma biology, with its upregulation potentially maintaining a less aggressive tumor phenotype and contributing to better outcomes." (PMID 40282990, 2025). "Despite its hallmark nuclear staining observed in gliomas, Olig2 immunoreactivity in melanoma was predominantly cytoplasmic." (PMID 37274223, 2023). "The loss of Olig2, an oligodendrocyte marker, is a well-described histopathologic finding of H3.3-G34R/V mutant gliomas, although focal positivity in co-occurring reactive glial cells has been described." (PMID 37509641, 2023). "Instead, glioma-associated oncogene 1 (GLI1) and oligodendrocyte lineage transcription factor 2 (OLIG2), the expression of which is highly associated with glioma and GSCs, were upregulated." (PMID 28830458, 2017). "Olig-2 is universally expressed in diffuse gliomas and serves as a diagnostic marker for brain tumor, especially for highly tumorigenic gliomas." (PMID 26136642, 2015). "Olig-2 is well recognized as a diagnostic marker for brain tumor, for it is required for proliferation of human glioma cells." (PMID 26136642, 2015). "As in our past studies, the GSCs also express high levels of the glioma stem cell marker encoded by Olig2." (PMID 20186265, 2010). "Notably, oligodendrocyte transcription factor 2 (Olig2) has emerged as a defining marker of glioma stem cells, which are strongly associated with tumor recurrence and resistance to conventional therapies." (PMID 41272822, 2025). "Additionally, OLIG2 has been shown to dictate glioma stem cell subtype identity, as its loss triggers a shift from the proneural transcriptional subtype to other subtypes." (PMID 41394801, 2025). "Furthermore, Olig2 has been implicated in the production of astrocyte subpopulations and cholinergic neurons in the developing CNS and the proliferation of glioma stem cells." (PMID 34974536, 2022). "Thus, Imaging-Community-AMARETTO (Appendix Fig A1) identified THBS1 and MAP2 as novel master drivers across the three STAT3, AHR, CCR2, and OLIG2 communities that provide new insights into how these distinct key mechanisms are linked in glioma." (PMID 32383980, 2020). "Characterization of the resulting cell line (mGb4) by IF and FACS revealed that cells express CD15, CD133, CD44 stem cell markers together with SOX2 and OLIG2, two transcription factors associated with the maintenance of multipotency and proliferation of glioma multipotent cells." (PMID 26953813, 2016). "Since loss of NF1 is a hallmark of mesenchymal glioma, it is possible that an increased subpopulation of Olig2+ cells may be a driver of oncogenesis in that tumor subtype." (PMID 23451236, 2013). "The strong frontal lobe preference of IDH1/2-mutant gliomas may be associated with their epigenetic features in OLIG2-positive precursor cells existing in this region, potentially driving selective expansion of IDH1/2-mutant clones through aberrant metabolic reprogramming." (PMID 41377022, 2025).
glioma (continued). "While Olig2 has been extensively studied in proneural GBM subtypes for its role in maintaining glioma stem cells (GSCs), our work highlights the cooperative function of Olig1/2 in astrocytic-featured GBM." (PMID 40428395, 2025). "Tumor progenitor populations in high-grade gliomas and oligodendrogliomas often express markers such as Olig2, Nkx2.2, and PDGFRα, supporting the concept that OPC-like cells act as critical drivers of glioma progression." (PMID 41272822, 2025). "According to scRNA-seq and qPCR-RT data, rat glioma 101.8 tumor cells are characterized by high expression levels of the oligodendroglial markers Olig1 and Olig2." (PMID 41009560, 2025). "Immunohistochemically, the glial tumor component expressed oligodendrocyte transcription factor 2 (Olig2)." (PMID 40234994, 2025). "Consistent with previously observed patterns in GBM specimens, OLIG2 expression was elevated in SW1783 and U251MG cells, while U87MG and LN229 cells exhibited characteristics associated with mesenchymal glioma cells." (PMID 39895794, 2025). "OLIG2, another neural transcription factor, plays a critical role in glioma development by maintaining cancer stem cell populations and supporting resistance to therapy." (PMID 40567599, 2025). "Certainly, the targeting of OLIG2 is feasible for gliomas in adults, but it should be noted that the degree of expression can vary in glioblastomas and astrocytoma while it is usually well expressed in oligodendrogliomas." (PMID 40677711, 2025). "Both Olig1 and Olig2 are ubiquitously expressed in gliomas and play pivotal roles in tumorigenesis and phenotypic plasticity." (PMID 40428395, 2025). "Genes involved in differentiation and immune response were found to be downregulated in IDH-mutant gliomas, while OLIG2, which is expressed in the normal adult brain, was overexpressed in gliomas." (PMID 41007824, 2025). "Genes linked to stemness and therapy resistance included CD133 (PROM1), SOX2, Nestin, OLIG2, and Musashi-1, all of which support the persistence of glioma stem-like cell populations and drive recurrence." (PMID 41179304, 2025). "We analyzed these cells for the expression of neural/stem precursor cell markers (OLIG1, OLIG2, CSPG4/NG2, NESTIN), which are also transcription factors and lineage markers associated with glioma stem cells (GSC), and DMRTA2." (PMID 38509074, 2024). "Other than NG2 proteoglycan, the vast majority of gliomas express other markers typical for OP, such as Olig-2 and PDGFRα, while NG2 and PDGFRα are key factors for cellular proliferation and motility." (PMID 39057054, 2024). "Among all of the glioma stem cells, the only ones related to the regulation of the cell cycle are OLIG-2 and cyclin D2." (PMID 39057054, 2024). "Similar to during gliogenesis, the levels and functional interactions of ASCL1 and OLIG2 then determine the cell types and degree of migration of glioma tumors that are generated." (PMID 39609428, 2024). "TAGLN co‐distributed with GSC markers CD133, CD15, SOX2, and OLIG2 in glioma cells, suggesting that TAGLN was preferentially expressed in GSCs in patient tissues." (PMID 38087889, 2024). "Especially, Olig2 is overexpressed in glioma stem cells (GSCs) compared with differential glioma cells and promotes GSCs proliferation through directly inhibiting p21WAF1/CIP which suggests Olig2 seems to be an important glioma stem cell biomarker." (PMID 36990974, 2023). "We chose OLIG2 as a root-state marker, as it had long been treated as stem cells of malignant glioma, and ordered cells to visualize the development of glioma cells." (PMID 36599974, 2023).
glioma (continued). "Further investigation on the mechanics of OLIG2 in promoting cGBM would help researchers get a better understanding of this type of glioma." (PMID 37001387, 2023). "Because Olig2 activity is regulated by Shh, it is plausible that increased levels of Olig2 in gliomas are contributed by Shh deregulation." (PMID 37274223, 2023). "Chromatin immunoprecipitation (ChIP) analysis demonstrated that p21 is a direct target of Olig2 repression in NPCs and gliomas." (PMID 37274223, 2023). "While observations of Olig2 expression have been conflicting in different types of gliomas, its upregulation was clearly indicated in oligodendrogliomas." (PMID 37274223, 2023). "As reported, Olig2 is a potentially highly specific glioma stem cell marker and plays significantly role in reprograming differentiated glioblastoma (GBM) cells into stemlike cells." (PMID 36990974, 2023). "More recently, it was reported that OLIG2 modulates growth factor signaling in two distinct populations of glioma stem-like cells depending on their EGFR or PDGFRα expression." (PMID 37511403, 2023). "We knocked down OLIG2 with specific targeting short hairpin RNAs (shRNAs) or siRNAs in patient-derived GSCs and glioma cells respectively, then found that INHEG expression was decreased upon OLIG2 downregulation as measured by qRT-PCR and western blotting." (PMID 37980347, 2023). "We confirmed that these cells lines were diffuse high-grade glioma as they were all positive for Olig2 except for J3T-Bg cell lines, and astrocytic type for those positive for GFAP and Vimentine." (PMID 38098992, 2023). "Re-characterization of Olig2 in “secondary GBM” samples is therefore necessary for thorough understanding of glioma pathogenesis." (PMID 37274223, 2023). "Increasing evidence has associated Shh signaling pathway with CNS tumors, however its relationship with Olig2 in gliomas is only beginning to be elucidated." (PMID 37274223, 2023). "Researchers also found that OLIG2-knockdown glioma stem cells, although accompanied by tumor growth rate reduction, exhibit mesenchymal characteristics such as increased invasion and drug resistance." (PMID 37001387, 2023). "In detail, WNT7A/B secretion by Olig2 + oligodendrocyte precursor-like glioma cells was observed to promote VCO and to be upregulated in response to anti-angiogenic treatment." (PMID 36691028, 2023). "Current research in cancer reveals Olig2 is also highly expressed in glioma and correlated with glioma cell proliferation in orthotopic patient-derived xenograft models." (PMID 36990974, 2023). "Genes associated with the neuronal differentiation pathway (Pcsk9, Runx1, Cebpb, Fzd4, Wnt7a, Ascl1, Fzd2, Edn3, Olig2, and Gpc2), gliomas (Shc1, Cdk4, E2f2, and Ccnd1), and cell cycle (Bub1b, Bub, Ccnb1, Ccnb2, and Cdc20) were significantly downregulated." (PMID 36147849, 2022). "In vivo lucanthone slowed tumor growth: reduced numbers of Olig2+ glioma cells, normalized tumor vasculature, and reduced tumor hypoxia." (PMID 35494072, 2022). "Glioma cells arise from astrocytes or oligodendrocytes and express the undifferentiated glial cell marker, Olig2." (PMID 36323680, 2022). "Phosphorylation of amino‐terminal S10, S13, and S14 regulates the mitosis of Olig2 and also controls the growth of glioma cells." (PMID 37786890, 2022). "Tumors collected from each IUE condition displayed high-grade glioma histology, expressed Olig2, and contained Gfap-positive reactive astrocytes." (PMID 35105861, 2022). "We first evaluated Olig2 expression by immunohistochemistry, a biomarker diffusely expressed in infiltrating gliomas, and which was a commonly utilized biomarker among our global collaborative group." (PMID 35014126, 2022).
glioma (continued). "Other BHLH family members are reported in cancer biology and clinical outcomes, especially brain cancers like ASCL1 in glioma and neuroblastoma, Olig2 in astrocytoma, and ATOH1 in medulloblastoma." (PMID 35806162, 2022). "We then analyzed the distribution of the glioma stem cell marker OLIG2 observing a statistically significant increase only in the core of TMZ-treated mice over time." (PMID 35970913, 2022). "METTL3 is also upregulated in glioblastoma, and silence of METTL3 inhibits the growth of glioma stem cells by downregulating POU3F2, SOX2, SALL2, OLIG2, and other glioma recombinant factors." (PMID 35571490, 2022). "The relative protein expression of MES markers MET and YKL-40 and the PN marker OLIG2 was detected in four different human glioma cell lines." (PMID 34381734, 2021). "OLIG2 is expressed in varying degrees in both pediatric and adult gliomas, with significant expression occurring in GSC populations of oligodendrogliomas." (PMID 34012965, 2021). "In glioma stem cells, Olig2 promotes cell proliferation through direct inhibition of p21WAF1/CIP1, a tumor suppressor." (PMID 33833342, 2021). "Olig2 protein is commonly promoted in adult gliomas controlling oligodendrocytes development and expressed mainly in LGG." (PMID 33669639, 2021). "In fact, loss of Olig2 in NG2+ OPCs has been shown to increase differentiation into astrocytes at the expense of OLs, and Olig2 deletion converts gliomas from proneural to astrocytic signatures." (PMID 34480532, 2021). "Accordingly, deletion of OLIG2 in a mouse model of glioma results in impaired tumor growth and a shift in cellular profiles toward an astro-glial expression pattern." (PMID 34012965, 2021). "In line with this classification, the tumors are positive for established glioma markers such as Gfap and Olig2 and show an intense staining for the proliferation marker Ki67." (PMID 33435218, 2021). "Previous studies found that Olig2 controls cell cycling and growth in malignant neural progenitors and plays an important role in glioma formation." (PMID 33833342, 2021). "Post-translational modifications to OLIG2 mediate migration and proliferation of both OPCs and GSCs in development and glioma, respectively." (PMID 34012965, 2021). "This crosstalk between unphosphorylated Olig2 with TGFβ thus serves an important role dictating the proliferative or invasive properties of glioma cells." (PMID 34012965, 2021). "The glial fibrillary acidic protein (GFAP) and oligodendrocyte lineage transcription factor 2 (OLIG2) are two such examples of glioma markers routinely assessed by IHC during diagnosis." (PMID 33673213, 2021). "Olig2 expression determines oligodendroglial differentiation and plays crucial role as a prognostic factor in glioma classification." (PMID 33669639, 2021). "For example, OLIG2, one of the four critical transcriptional factors of glioma stem cells, has a high expression in proneural GBM, which associates with relatively poor prognosis and drug resistance." (PMID 34565408, 2021). "In a study done on glioma cells, cell motility decreased following the overactivation of RhoA using oligodendrocyte lineage transcription factor 2 (OLIG2)." (PMID 32089990, 2020). "qPCR analyses confirmed upregulation of Pdgfra, Olig2, Nestin, and Gfap in gliomas, compared with matched normal brain tissue from control littermates." (PMID 32142668, 2020). "In malignant glioma cells, OLIG2/DLL3 and AQP4/CLU distinguish tumor cells exhibiting transcriptomic features of oligodendrocytes and astrocytes, respectively." (PMID 34692159, 2020). "The oligodendrocyte transcription factor 2 (Olig2) was identified as a marker for glioma stem cells, which are believed to be responsible for glioma recurrence and therapy resistance." (PMID 32160197, 2020).